BTK (Bruton tyrosine kinase)
Diseases named in the same sentence as BTK in open-access papers (continued):
Sharing a sentence is not in itself a finding about the gene and the disease.
chronic lymphocytic leukemia (continued). "Among B cell malignancies, those in which the most significant results were obtained by BTK targeting are chronic lymphocytic leukemia/small lymphoma (CLL/SLL), mantle cell lymphoma (MCL), lymphoplasmacytic lymphoma (LPL), and diffuse large B cell lymphoma (DLBCL)." (PMID 38542207, 2024). "Ibrutinib was the first BTK inhibitor to be approved, and it changed the standard-of-care treatment for diseases such as chronic lymphocytic leukemia, mantle cell lymphoma, marginal zone lymphoma, and Waldenström macroglobulinemia, improving efficacy outcomes and safety compared to chemotherapy." (PMID 37696810, 2023). "BTK inhibition by IBN has been shown to cause lymphocytosis, a process of compartment shifts of tumor cells from lymphoid tissues to the periphery, in patients with chronic lymphocytic leukemia or MCL." (PMID 36719376, 2023). "Drugs targeting BTK may act as B cell receptor signaling pathway inhibitors to be involved in chronic lymphocytic leukemia regime by regulating B cell differentiation." (PMID 38071755, 2023). "Ibrutinib, an irreversible inhibitor of Bruton tyrosine kinase (BTK), has become a key molecule in the treatment of chronic lymphocytic leukemia (CLL), mantle cell lymphoma (MCL), Waldenström macroglobulinemia (WM), diffuse large B-cell lymphoma (DLBCL), and follicular lymphoma." (PMID 38055081, 2023). "The treatment landscape for patients with chronic lymphocytic leukemia (CLL) has changed considerably with the introduction of very effective oral targeted therapies (such as Bruton tyrosine kinase inhibitors and venetoclax) and next-generation anti-CD20 monoclonal antibodies (such as obinutuzumab)." (PMID 36446777, 2022). "Ibrutinib is an irreversible Bruton tyrosine kinase inhibitor that is approved for the treatment of mantle cell lymphoma, chronic lymphocytic leukemia, small lymphocytic lymphoma, Waldenström macroglobulinemia, marginal zone lymphoma, and mantle cell lymphoma." (PMID 35449638, 2022). "Phase 3 clinical trials of BTK inhibitors in relapsed/refractory chronic lymphocytic leukemia." (PMID 35159041, 2022). "In our case, the presumptive diagnosis was recurrent hyphema possibly related to coagulation abnormalities inherent in the patient’s chronic lymphocytic leukemia, with the patient’s treatment with BTK inhibitor ibrutinib also inhibiting BTK-dependent platelet aggregation." (PMID 35741122, 2022). "eTable 3 in the Supplement shows the large range of achieved antibody levels after vaccination stratified by cancer diagnosis and treatment type, with especially low levels observed among patients with chronic lymphocytic leukemia and those treated with BTK inhibitors and venetoclax." (PMID 35266953, 2022). "In recent years, new compounds targeting Bruton’s tyrosine kinase (BTK) have successfully been introduced in the treatment algorithm of chronic lymphocytic leukemia (CLL) and other B-cell neoplasms, pioneering a major therapeutic shift from chemoimmunotherapy to targeted therapy." (PMID 35326454, 2022). "One important example is ibrutinib, a small molecule designed to target Bruton’s tyrosine kinase (BTK) that was successfully used in clinical practice for the treatment of chronic lymphocytic leukemia (CLL), mantle cell lymphoma (MCL), and Waldenstrom’s macroglobulinemia." (PMID 34829820, 2021). "Given that BTK inhibitors have been FDA approved for chronic lymphocytic leukemia/small lymphocytic lymphoma and that the majority of BTK studies have been focused on B cells, the use of BTK inhibitors as a future treatment strategy of solid tumors has yet to be evaluated." (PMID 34063667, 2021). "Studies using the less specific BTK inhibitor ibrutinib, which is approved for the treatment of certain cancers such as mantle cell or chronic lymphocytic leukemia, may help to understand the role of BTK in microglia and/or astrocytes." (PMID 33801644, 2021).
chronic lymphocytic leukemia (continued). "Bruton tyrosine kinase (BTK), a member of the Tec tyrosine kinases family, plays a central role in B cell lymphomas, and BTK inhibitors are increasingly replacing chemotherapy-based regimens, particularly in patients with chronic lymphocytic leukemia and MCL." (PMID 34633777, 2021). "In addition to the role in normal B-cells development, the BTK high expression has long been known in B-cell malignancies (e.g., multiple myeloma, mantle cell lymphoma, and chronic lymphocytic leukemia)." (PMID 34440129, 2021). "In addition, BTK inhibitors decreased inflammatory cytokine levels in chronic lymphocytic leukemia, Waldenstrom’s macroglobulinemia, and graft-versus-host disease." (PMID 32932930, 2020). "Recently, the multi-kinase inhibitor ArQule 531 (ARQ 531) has demonstrated potent inhibition of SFK and BTK that translated to improved pre-clinical in vivo activity as compared with the irreversible BTK inhibitor ibrutinib in chronic lymphocytic leukemia (CLL) models." (PMID 31992353, 2020). "Besides, NKG2A single blockade for the therapy of gynecologic malignancies (NCT02459301), or in combination with ibrutinib (a BTK inhibitor) for the therapy of chronic lymphocytic leukemia (CLL) (NCT02557516), are also under clinical trials." (PMID 31552017, 2019). "Ibrutinib, a covalent inhibitor of Bruton tyrosine kinase (BTK), caused selective and durable downregulation of PD-L1 on chronic lymphocytic leukemia cells within 3 months of therapy, which was mediated through the inhibition of constitutively active STAT3 on these cells." (PMID 29580288, 2018). "BTK has emerged as a new molecular target for the treatment of B-lineage leukaemias and lymphomas, and Ibrutinib is the first BTK-specific inhibitor that entered the clinic, having been recently approved for the treatment of mantle cell lymphoma and chronic lymphocytic leukaemia." (PMID 26804170, 2016). "Similarly, the role of BTK in various other malignancies like Chronic Lymphocytic Leukemia (CLL), Mantle Cell Lymphoma (MCL) and Waldenstrom's Macroglobulinemia (WM) is well established and clinical trials using Ibrutinib has shown favorable outcomes." (PMID 26158763, 2015). "BTK inhibitors (BTKi) have become standard of care for treatment of patients with chronic lymphocytic leukemia (CLL)." (PMID 42098067, 2026). "Selective Bruton tyrosine kinase (BTK) inhibitors, such as ibrutinib and zanubrutinib, have been widely used as effective and well-tolerated treatments for chronic lymphocytic leukemia (CLL) and mantle cell lymphoma (MCL)." (PMID 40815495, 2025). "Bruton tyrosine kinase inhibitors (BTKis) are a key class of targeted therapies for B-cell malignancies such as chronic lymphocytic leukemia (CLL) and mantle cell lymphoma (MCL)." (PMID 40421329, 2025). "Common medications used to treat newly diagnosed and relapsed/refractory chronic lymphocytic leukemia (CLL) include Bruton tyrosine kinase inhibitors (BTKi) and B-cell lymphoma-2 inhibitors (BCL-2)." (PMID 39858050, 2025). "Concurrently, novel agents (NAs) like venetoclax and Bruton tyrosine kinase inhibitors (BTKIs) have revolutionized the treatment of chronic lymphocytic leukemia (CLL)." (PMID 38893198, 2024). "The treatment of chronic lymphocytic leukemia (CLL) consists of the continuous use of Bruton tyrosine kinase inhibitors (BTKis) such as ibrutinib, acalabrutinib, zanubrutinib and pirtobrutinib, or Bcl-2 inhibitors, such as venetoclax." (PMID 39830358, 2024). "Ibrutinib was the first Bruton's tyrosine kinase (BTK) inhibitor approved for the treatment of patients with chronic lymphocytic leukemia (CLL)." (PMID 38829647, 2024). "Bruton tyrosine kinase (BTK) inhibitor therapy induces peripheral blood lymphocytosis in chronic lymphocytic leukemia (CLL), which lasts for several months." (PMID 39436708, 2024). "Inhibitors of Bruton’s tyrosine kinase (BTK) have changed how we treat chronic lymphocytic leukemia (CLL), a B cell malignancy." (PMID 39518015, 2024).
chronic lymphocytic leukemia (continued). "In chronic lymphocytic leukemia (CLL), BTK is upregulated, contributing to a continuously activated BCR signaling pathway." (PMID 37771591, 2023). "In recent years, the introduction of new drugs targeting Bruton’s tyrosine kinase (BTK) has allowed dramatic improvement in the prognosis of patients with chronic lymphocytic leukemia (CLL) and other B-cell neoplasms." (PMID 35326454, 2022). "The advent of BTK inhibitors has revolutionized the treatments of B cell malignancies, especially chronic lymphocytic leukemia/small lymphocytic lymphoma (CLL/SLL) and mantle cell lymphoma (MCL)." (PMID 35379357, 2022). "The advent of BTK inhibitors has changed the treatment of patients with chronic lymphocytic leukemia (CLL) and mantle cell lymphoma (MCL)." (PMID 35379357, 2022). "Selinexor is currently in a phase 1 clinical trial for chronic lymphocytic leukaemia (CLL) in combination with the BTK inhibitor ibrutinib and the addition of NK cell adoptive transfer/CAR-NK cells and/or combination with an anti-CD20 antibody may further improve clinical responses (NCT02303392)." (PMID 36560403, 2022). "Recent studies suggested that ibrutinib, a Bruton tyrosine kinase (BTK) inhibitor, developed for the treatment of chronic lymphocytic leukemia, may prevent NLRP3 inflammasome activation in macrophages, IL-1β secretion and subsequent development of inflammation and organ fibrosis." (PMID 34099830, 2021). "BTK inhibitors, such as ibrutinib, acalabrutinib, and zanubrutinib, are currently being used in clinical trials for hematologic malignancies, including B cell lymphoma, mantle cell lymphoma, and chronic lymphocytic leukemia/small lymphocytic lymphoma, with promising results." (PMID 34063667, 2021). "Ibrutinib, a Bruton tyrosine kinase inhibitor, provides effective treatment for chronic lymphocytic leukemia (CLL)." (PMID 31996669, 2020). "Ibrutinib (ibr), a first-in-class BTK inhibitor, has demonstrated high response rates in both relapsed/refractory and treatment naïve chronic lymphocytic leukemia (CLL)." (PMID 27626698, 2016). "The first-in-class BTK inhibitor, ibrutinib, has been in clinical use for the treatment of chronic lymphocytic leukemia (CLL), mantle cell lymphoma, and Waldenstrom’s macroglobulinemia." (PMID 26957112, 2016). "In relapsed/refractory (RR) chronic lymphocytic leukaemia (CLL), Bruton tyrosine kinase inhibitors (BTKi) are administered as monotherapy until disease progression." (PMID 42120657, 2026). "Therapy for chronic lymphocytic leukemia (CLL) has evolved dramatically with the introduction of targeted agents, particularly Bruton tyrosine kinase inhibitors (BTKis) and BCL2 inhibitors (BCL2is)." (PMID 42278639, 2026). "Ibrutinib is a first-generation Bruton tyrosine kinase (BTK) inhibitor that became standard of care for the treatment of many B-cell malignancies, including chronic lymphocytic leukemia and mantle cell lymphoma." (PMID 40560431, 2025). "Currently, four small-molecule BTK inhibitors have been approved by the U.S. Food and Drug Administration (FDA) for treatment of mantle cell lymphoma, chronic lymphocytic leukemia and small lymphocytic lymphoma." (PMID 41199836, 2025). "The treatment landscape of chronic lymphocytic leukemia (CLL) has been reshaped over the past decade, largely due to the approval of small molecule inhibitors targeting Bruton’s tyrosine kinase (BTK) and the anti‐apoptotic protein B‐cell lymphoma 2 (BCL2)." (PMID 41328215, 2025). "In chronic lymphocytic leukemia (CLL), covalent Bruton tyrosine kinase (BTK) inhibitors exert their activity by binding to cysteine residue 481 of the BTK protein." (PMID 41247642, 2025). "Orelabrutinib, a second-generation BTK inhibitor, has shown potential clinical efficacy in chronic lymphocytic leukemia (CLL), small lymphocytic lymphoma (SLL), mantle cell lymphoma (MCL), and relapsed or refractory Waldenström macroglobulinemia." (PMID 40599858, 2025).
chronic lymphocytic leukemia (continued). "A phase Ib/II trial (NCT04234061) is evaluating epcoritamab in combination with the BTK inhibitor ibrutinib in patients with R/R mantle cell lymphoma (MCL) and chronic lymphocytic leukemia (CLL)." (PMID 39997328, 2025). "These agents have shown impressive clinical activity in chronic lymphocytic leukemia (CLL) and mantle cell lymphoma (MCL), making BTK inhibition the preferred front-line therapy." (PMID 41266486, 2025). "BTK plays a crucial role in the BCR signaling pathway and the biology and clinical course of CLL and small lymphocytic lymphoma (SLL)." (PMID 39941798, 2025). "Ibrutinib, an oral inhibitor of Bruton tyrosine kinase (BTK), is used to treat mantle cell lymphoma, chronic lymphocytic leukemia, and Waldenström macroglobulinemia." (PMID 41199910, 2025). "Pathway inhibitors targeting Bruton tyrosine kinase (BTK) and B-cell lymphoma-2 (BCL-2) have dramatically changed the treatment landscape for both treatment-naïve and relapsed/refractory chronic lymphocytic leukemia (CLL)." (PMID 39858050, 2025). "Management of chronic lymphocytic leukemia (CLL), in first-line and relapsed/refractory settings, has been revolutionized by the introduction of oral, targeted agents against Bruton Tyrosine Kinase (ibrutinib), PI-3Kinase (idelalisib), and Bcl-2 (venetoclax)." (PMID 39037964, 2024). "The enzyme Bruton tyrosine kinase (BTK) is involved in B-cell signaling that promotes the migration, proliferation, and survival of neoplastic B-cells of patients with chronic lymphocytic leukemia (CLL)." (PMID 39048721, 2024). "Ibrutinib: Ibrutinib, an irreversible BTK inhibitor, was initially approved by the FDA in 2013 for the treatment of mantle cell lymphoma (MCL) and later in 2014 for chronic lymphocytic leukemia (CLL) and in 2015 for Waldenström’s macroglobulinemia." (PMID 38033434, 2023). "Ibrutinib is a medication that blocks the activity of a protein called Bruton's tyrosine kinase (BTK) and is primarily used as a first-line agent for treating chronic lymphocytic leukemia (CLL)." (PMID 38130705, 2023). "The development of inhibitors of B-cell receptor (BCR) signalling, particularly those that inhibit Bruton tyrosine kinase (BTK), has transformed the treatment landscape for chronic lymphocytic leukaemia (CLL) over the last decade." (PMID 37174062, 2023). "Clinically, long-term treatment with ibrutinib, an inhibitor that forms irreversible covalent bonds to BTK, reversed CD8 T cell exhaustion and protected T cells from proliferation-induced senescence in chronic lymphocytic leukemia (B-CLL) patients." (PMID 37153607, 2023). "Zanubrutinib (ZB), a second-generation BTK inhibitor, is currently used in the treatment of capsid cell lymphoma (MCL) and chronic lymphocytic leukemia/small lymphocytic lymphoma (CLL/SLL)." (PMID 37630287, 2023). "Bruton’s tyrosine kinase (BTK) plays a key role in the B-cell receptor (BCR) signaling pathway and confers anti-apoptotic and proliferative properties to malignant B-cells in chronic lymphocytic leukemia (CLL)." (PMID 38137005, 2023). "The first-in-class BTK inhibitor approved by the Food and Drug Administration (FDA) in the US was ibrutinib for the treatment of chronic lymphocytic leukaemia (CLL) and mantle cell lymphoma." (PMID 34894949, 2022). "The use of Bruton’s tyrosine kinase (BTK) inhibitors has changed the management and clinical history of patients with chronic lymphocytic leukemia (CLL)." (PMID 35159041, 2022). "Targeting B-cell receptor signalling using Bruton tyrosine kinase (BTK) inhibitors (BTKis) has become a highly successful treatment modality for B-cell malignancies, especially for chronic lymphocytic leukaemia." (PMID 36138486, 2022). "Ibrutinib is a potent, irreversible and effective inhibitor of BTK that is taken orally, and was approved for indications in mantle cell lymphoma (MCL) and chronic lymphocytic leukemia (CLL) in 2013 and 2014." (PMID 35115740, 2022).
chronic lymphocytic leukemia (continued). "A possible example of this is the treatment of chronic lymphocytic leukemia (CLL) with ibrutinib, a kinase inhibitor that targets BTK on the malignant B cells and ITK on the T cells." (PMID 35844298, 2022). "Ibrutinib is a first-in-class, once-daily oral inhibitor of Bruton’s tyrosine kinase (BTK) approved in Europe as monotherapy for the treatment of adult patients with previously untreated and relapsed/refractory (R/R) chronic lymphocytic leukemia (CLL)." (PMID 36227519, 2022). "Interestingly, BTK is the target of Ibrutinib and other second-generation inhibitors used in the treatment of B-cell chronic lymphocytic leukemia (CLL)." (PMID 35128378, 2022). "Targeted therapies against phosphatidylinositol 3-kinase (PI3K), Bruton’s tyrosine kinase (BTK), and B-cell lymphoma-2 (BCL-2) are approved for chronic lymphocytic leukemia (CLL)." (PMID 35999205, 2022). "A Bruton tyrosine kinase (BTK) inhibitor and hematopoietic cell kinase (HCK) inhibitor are used in the treatment of chronic lymphocytic leukemia, mantle cell lymphoma, and Waldenstrom’s macroglobulinemia." (PMID 33912588, 2021). "The BTK inhibitor used, Ibrutinib (Imbruvica®, previously PCI-32765), is a first-in-class irreversible inhibitor of BTK and is FDA approved for chronic lymphocytic leukemia." (PMID 35008785, 2021). "BGB-3111, a novel Bruton’s tyrosine kinase (BTK) inhibitor, shows promising anti-cancer effects in chronic lymphocytic leukemia/small lymphocytic lymphoma (CLL/SLL), mantle cell lymphoma (MCL), and Waldenstrom macroglobulinemia (WM)." (PMID 34508613, 2021). "The orally administered, bioavailable BTK inhibitor ibrutinib has been FDA-approved to treat patients with relapsed mantle cell lymphoma (MCL), Waldenstrom’s macroglobulinemia, and chronic lymphocytic leukemia (CLL), including those harboring 17p deletion." (PMID 33946867, 2021). "Ibrutinib is an irreversible Bruton’s tyrosine kinase (BTK) inhibitor and is approved by the FDA for various B cell cancers including chronic lymphocytic leukemia." (PMID 34880215, 2021). "Ibrutinib, a Bruton tyrosine kinase (BTK) inhibitor, has become a standard in the treatment of chronic lymphocytic leukemia (CLL) patients." (PMID 33477957, 2021). "The therapeutic landscape of chronic lymphocytic leukemia (CLL) underwent a paradigm shift in 2014 with the approval of ibrutinib, which binds covalently to the C481 residue of Bruton’s tyrosine kinase (BTK) and irreversibly inhibits it." (PMID 33718939, 2021). "Nowadays, many patients with chronic lymphocytic leukemia (CLL) are treated with so-called novel agents, including BTK inhibitors, Bcl-2 inhibitors and PI3K inhibitors." (PMID 33809580, 2021). "Pathway inhibitors (PI) such as BTK-inhibitors (BTKi), PI3-Kinase inhibitors (PI3Ki), and BCL2-inhibitors (BCL2i) have fundamentally transformed the standard treatment landscape for chronic lymphocytic leukemia (CLL) in recent years." (PMID 33004942, 2021). "Bruton’s tyrosine kinase (BTK) is a critical component in B-cell receptor signaling, and the BTK inhibitor, ibrutinib, is FDA approved to treat B-cell chronic lymphocytic leukemia." (PMID 32983132, 2020). "The development of drugs able to target BTK, PI3k‐delta and BCL2 has dramatically improved chronic lymphocytic leukaemia (CLL) therapies." (PMID 31821686, 2020). "These BTK functions are essential in survival and proliferation of malignant cells in various non-Hodgkin lymphomas (NHL), such as chronic lymphocytic leukemia (CLL) and mantle cell lymphoma (MCL)." (PMID 33322351, 2020). "In 2014, ibrutinib, a Bruton’s tyrosine kinase (BTK) inhibitor, at a dose of 420 mg po daily, was approved as second line treatment for chronic lymphocytic leukemia (CLL), based on the RESONATE landmark trial, leading to FDA approval for this indication." (PMID 32503582, 2020).